SUFU (SUFU negative regulator of hedgehog signaling)
Description:
Negative regulator in the hedgehog/smoothened signaling pathway that acts by sequestering the GLI (GI1, GLI2 and GLI3) transcription factors in the cytoplasm. When smoothened signaling is initiated, GLI transcription factors dissociate from SUFU, translocate to the nucleus and activate expression of target genes. In absence of smoothened signaling, the SUFU-GLI3 complex is recruited to cilia, leading to the efficient processing of full-length GLI3 into transcription repressor GLI3R: SUFU participates to GLI3 processing by promoting recruitment of GSK3B to GLI3. May also act as a negative regulator of beta-catenin signaling (By similarity). Required for normal embryonic development (By similarity). Required for the proper formation of hair follicles and the control of epidermal differentiation (By similarity).
Synonyms: SUFUH; SUFUXL; PRO1280; BCNS2; JBTS32
Tractability: Small molecule: it has a high-quality binding pocket. PROTAC: UniProt records ubiquitination sites on it; ubiquitination databases record sites on it.
Gene: Protein-coding gene on chromosome 10 (102,503,952 to 102,633,535, forward strand). Ensembl gene ENSG00000107882.
Subcellular location: Cytoplasm; Nucleus; Cell projection, cilium
Subcellular location (Human Protein Atlas): Nucleoplasm; Primary cilium
Pathways (Reactome):
Signal Transduction: Degradation of GLI1 by the proteasome; Degradation of GLI2 by the proteasome; GLI3 is processed to GLI3R by the proteasome; Hedgehog 'off' state; Hedgehog 'on' state
Gene Ontology:
Molecular function: protein binding; protein kinase binding; protein sequestering activity; transcription corepressor activity; beta-catenin binding; protein-macromolecule adaptor activity
Biological process: negative regulation of smoothened signaling pathway; negative regulation of transcription by RNA polymerase II; regulation of DNA-templated transcription; negative regulation of osteoblast differentiation; negative regulation of protein import into nucleus; signal transduction; positive regulation of cellular response to drug; positive regulation of protein processing; spermatid development
Cellular component: cytoplasm; GLI-SUFU complex; nucleoplasm; nucleus; ciliary base; ciliary tip; cytosol; cilium; non-motile cilium
Genetic constraint (gnomAD): Loss-of-function variants: 7 observed, 61.48 expected, observed/expected ratio (o/e) 0.11, 90% interval 0.064 to 0.21. The upper end of that interval is the gene's LOEUF score, 0.21, which puts it in group 1 of 6, group 1 being the genes least tolerant of losing a copy. Missense variants: 451 observed, 673.29 expected, observed/expected ratio (o/e) 0.67, 90% interval 0.62 to 0.72. Synonymous variants: 232 observed, 264.47 expected, observed/expected ratio (o/e) 0.88, 90% interval 0.79 to 0.98.
Gene-disease validity (ClinGen):
ClinGen rates the evidence that SUFU causes each of these diseases.
medulloblastoma (autosomal dominant): Definitive. A malignant, invasive embryonal neoplasm arising from the cerebellum.
ciliopathy (autosomal recessive): Limited. A genetic disorder of the cellular cilia or the cilia anchoring structures, the basal bodies, or of ciliary function.
Cancer hallmarks: invasion and metastasis (promotes); suppression of growth (promotes); invasion and metastasis (suppresses); angiogenesis (suppresses); escaping programmed cell death; angiogenesis
Homologues: Orthologues: dog SUFU (99% identical), rabbit SUFU (99% identical), guinea pig SUFU (98% identical), pig SUFU (98% identical), mouse Sufu (98% identical), rat Sufu (98% identical), chimpanzee SUFU (96% identical), macaque SUFU (94% identical), tropical clawed frog sufu (87% identical), zebrafish sufu (82% identical), Drosophila melanogaster Su(fu) (38% identical).
Diseases named in the same sentence as SUFU in open-access papers:
SUFU is named in the same sentence as 97 diseases in open-access papers, as found by Europe PMC text mining. Sharing a sentence is not in itself a finding about the gene and the disease. The quoted sentences say what the papers report.
medulloblastoma (61 papers, 2007 to 2026). "Nevertheless, in medulloblastoma, a mutation in SUFU increases SUFU turnover, leading to sustained HH signaling activation, which is associated with the worst prognosis." (PMID 40565349, 2025). "In general, BCNS patients with SUFU variants have an increased risk of developing medulloblastoma compared to those carrying PTCH1 mutations." (PMID 37504252, 2023). "In the setting of sporadic cancers, somatic deleterious mutations and deletions of PTCH1 and SUFU have been observed in a subset of BCCs and medulloblastomas." (PMID 37255594, 2023). "Individuals with an SUFU pathogenic mutation (33%) have a much higher occurrence of medulloblastoma than those with a PTCH1 pathogenic variant (2%)." (PMID 37629084, 2023). "Together, these findings can explain the preference for SUFU mutations in infant medulloblastoma and suggest that drugs targeting the downstream SHH pathway will be most appropriate for infant patients." (PMID 35535520, 2022). "Refined diagnoses were observed in two cases of medulloblastoma via the presence of a loss-of-function variant in SUFU (P2803) and an activating missense variant in MYCN (P2624)." (PMID 35449451, 2022). "Germline mutations in known tumor suppressor SUFU on chromosome 10 have long been associated with childhood medulloblastoma, with loss of SUFU leading to disruptions in the sonic hedgehog signaling pathway." (PMID 36686824, 2022). "Other novel genes identified in this study are associated with cancer, such as WDR20 with medulloblastoma and SUFU with renal cell carcinoma." (PMID 33809095, 2021). "Patient characteristics for the Gorlin M0 Cohort (all genetically diagnosed PTCH1 and SUFU associated Gorlin syndrome patients) vs. the Comparative M0 Cohort (all medulloblastomas (MB), SHH+, M0, <4y)." (PMID 34888241, 2021). "Specifically, medulloblastoma was found in 3 out of 9 individuals (33.3%) with SUFU variants, but in only 2 out of 115 patients (1.7%) with PTCH1 variants." (PMID 33441926, 2021). "Germline mutations in SUFU are implicated in Gorlin syndrome and predisposition to childhood medulloblastoma." (PMID 34357098, 2021). "In a large series of medulloblastomas screened for germline mutations, all SUFU or PTCH1 PVs were observed exclusively in the SHH-medulloblastoma (SHH-MB) subgroup, with a frequency of 17/80 (21%) and 18/170 (11%) in infant and pediatric SHH MB, respectively." (PMID 33860896, 2021). "In humans, the loss of SUFU function has been shown to be associated with the tumorigenesis and progression in many cancers, such as medulloblastoma, basal cell carcinoma, and rhabdomyoma, indicating that SUFU is a tumor suppressor gene." (PMID 34021128, 2021). "The risk of developing medulloblastoma is substantially higher in individuals with SUFU mutations (33%) than in those with PTCH1/2 pathogenic variants (<2%)." (PMID 35096710, 2021). "The prevalence of medulloblastoma in GS is significantly higher in patients with the SUFU gene mutation (33%) than in patients with the patched 1 (PTCH1) gene mutation (<2%)." (PMID 33066274, 2020). "Though none of our study subjects had a history of medulloblastoma, a germline pathogenic variant in SUFU has previously been strongly associated with medulloblastomas." (PMID 31485359, 2019). "Our findings uncover mechanisms controlling the tumour suppressive functions of SuFu and reveal that their alterations are implicated in medulloblastoma tumorigenesis." (PMID 29515120, 2018). "Suppressor of Fused (SuFu), a tumour suppressor mutated in medulloblastoma, is a central player of Hh signalling, a pathway crucial for development and deregulated in cancer." (PMID 29515120, 2018).
medulloblastoma (continued). "Germline and somatic mutations of SuFu described in patients with medulloblastoma alter SuFu repressor functions." (PMID 29515120, 2018). "A germline mutation of SUFU has been reported only in 6 patients, 5 of whom developed medulloblastoma." (PMID 23951062, 2013). "Mutations in human SUFU have been found in medulloblastoma and prostate cancer, and SUFU loss of heterozygosity was observed in rhabdomyosarcoma (RMS), implicating that SUFU is a tumor suppressor gene." (PMID 22666390, 2012). "Mutations in Sonic Hedgehog (SHH) pathway genes (PTCH1, SUFU) are found in approximately 25% of medulloblastomas, and in WNT pathway genes (β-catenin, APC, AXIN) in approximately 15% of the cases." (PMID 18769486, 2008). "The mutation of SUFU predisposes to the sonic hedgehog medulloblastoma." (PMID 38858783, 2024). "Interestingly, PTCH1 and SMO pathogenic mutations are substantially more frequent in sporadic medulloblastoma than SUFU pathogenic mutations are." (PMID 37629084, 2023). "Medulloblastomas tend to be associated with “suppressor of fused homologue” (SUFU) gene mutations." (PMID 37887561, 2023). "Similarly, SUFU, the negative regulator of HH signaling, is also commonly mutated in Gorlin syndrome-related medulloblastomas." (PMID 37255594, 2023). "Notably, different SuFu mutations occurring in medulloblastoma patients are insensitive to Itch activity, thus leading to deregulated Hh signalling and enhancing medulloblastoma cell growth." (PMID 29515120, 2018). "Analysis of GLI1 protein expression in SUFU-positive and SUFU-deficient human medulloblastoma cells and Sufu knockout mouse embryonic fibroblasts further corroborated the potent activity of DYRKi to inhibit GLI activity in SMO-inhibitor sensitive and resistant cells." (PMID 26784250, 2016). "Importantly, for the remaining nine PGVs that were identified in genes with a strong association with familial glioblastoma or medulloblastoma (SUFU, MSH6 (2x), PMS2 (5x) and BRCA1), a second (somatic) event and/or a matching mutational signature was identified in the tumor." (PMID 41168197, 2025). "Hence, if a subset of infant medulloblastoma is derived from the earliest specified CGNPs, this could explain the increased frequency of SUFU mutations, as these cells are less frequently ciliated." (PMID 35535520, 2022). "Importantly, DYRK1B targeting abolished GLI1 expression in SMO-inhibitor sensitive and SMO-inhibitor resistant cells including SUFU deficient medulloblastoma, GLI1-dependent pancreatic cancer and Ewing sarcoma cells expressing GLI1 in response to the EWS-FLI1 oncoprotein." (PMID 26784250, 2016). "Approximately 30% of medulloblastomas and occasionally rhabdomyosarcomas have abnormal activation of the Hh pathway, which is often due to PTCH or SUFU mutations." (PMID 35163655, 2022). "In human medulloblastoma, mutations in PTCH1, SMO, and SUFU, and amplifications of SHH, GLI2, and MYCN, a pathway target gene, have been identified." (PMID 36010600, 2022). "Using a genome-wide transposon mutagenesis screening in Hh-dependent medulloblastoma cells, SUFU and oral facial digital syndrome 1 (OFD1) were identified as culprit genes." (PMID 35163655, 2022). "This autonomous activation occurs in BCC and medulloblastoma and results from loss-of-function mutations in PTCH or SUFU, or gain-of-function mutations in SMO." (PMID 35163655, 2022).
medulloblastoma (continued). "SHH is the predominant group in adult medulloblastomas, and adult SHH tumours are characterised by upstream pathway mutations in PTCH1 and SMO, whereas downstream pathway alterations such as SUFU mutations and MYCN amplifications are rare in this age group." (PMID 33172502, 2020). "In the SHH-activated medulloblastoma cases, 2 SHH pathway specific mutations in SUFU (MB_5) or PTCH1 (MB_2) were detected." (PMID 32758285, 2020). "In particular, germline mutations in Patched1 have been found to be responsible for somatic mutations in medulloblastoma, and 50% of medulloblastomas present loss of PTCH1, loss of SUFU, or gain-of-function of SMO." (PMID 33050158, 2020). "SuFu is a tumour suppressor in medulloblastoma and regulates Gli proteins in the Sonic Hedgehog pathway; however, the molecular mechanisms behind this regulation are unclear." (PMID 29515120, 2018). "Activating mutations in the key components of the SHH pathway PTCH1, SMO and SUFU have been described in medulloblastoma and basal cell carcinoma." (PMID 27825128, 2016). "This type of signaling has been observed in basal cell carcinoma (PTCH and SMO mutations), medulloblastoma (PTCH and SUFU mutations), and rhabdomyosarcoma (PTCH and SUFU loss of heterozygosity)." (PMID 24598114, 2014). "Among them, mutations and deletions of the Shh pathway components PTCH1, Suppressor of fused (SUFU), and RENKDCT11 have been implicated in medulloblastoma." (PMID 23951168, 2013). "Similarly, chromosome 9 and 10, commonly deleted in these cancers, contain several important suppressor genes such as CDKN2A and PTEN in glioma; XPA, PPP6C, and CDKNA in melanoma; PTCH1 and SUFU in medulloblastoma." (PMID 41537310, 2026). "Similar to SUFU, GPR161 variants seem to be found primarily in infant medulloblastoma; previously reported in 3.4% of pediatric SHH medulloblastoma cases (5 of 6 of our reported cases were under the age of 12 months), compared to only one 10-year-old case with a P/LP GPR161 variant in our cohort." (PMID 39184053, 2024). "We identified P/LP variants in four of the six medulloblastoma genes: APC, ELP1, GPR161, and SUFU." (PMID 39184053, 2024). "In line with this, mice with conditional Sufu deletion in robust GLI2 expression background display reduced GLI activity and have significantly prolonged survival of medulloblastoma-prone mice, indicating the biphasic and contextual roles of SUFU with regard to tumor formation." (PMID 37213270, 2023).
medulloblastoma (continued). "Our results are in good agreement with this observation since none of the investigated patients presented with medulloblastoma and none had causative variants in SUFU." (PMID 37504252, 2023). "Patients with SUFU mutations have a significantly increased risk of developing medulloblastoma; however, no patient diagnosed as GS with SUFU mutations has been reported to develop KCOT." (PMID 33066274, 2020). "Medulloblastoma associated with pathogenic SUFU variants usually emerges earlier than nonhedgehog related medulloblastomas." (PMID 31485359, 2019). "Our study presents four cases of GS in one family due to a frameshift variant in SUFU, three of which have developed meningiomas but no medulloblastomas." (PMID 31485359, 2019). "Importantly, 4SC‐202 but not the FDA‐approved inhibitor vismodegib, efficiently abrogated HH/GLI signaling in SUFU‐depleted human medulloblastoma cells resistant to SMOi‐therapy." (PMID 29055107, 2018). "In particular, human medulloblastomas of the SHH subgroup, accounting for ~30% of all medulloblastomas, arise mostly due to mutations in the PTCH1 receptor, the transmembrane activator Smoothened, the signal transduction modulator SUFU and transcriptional regulator GLI2." (PMID 25901736, 2015). "Natural selection due to the high incidence of lethal medulloblastoma might have decreased the SUFU-mutant pedigrees more than the Ptch1-mutant pedigrees." (PMID 23951062, 2013). "In addition, inactivating mutations of PTCH1 and SUFU and activating mutations of SMOH account, in total, for at least 20% of all cases of medulloblastoma in humans." (PMID 20520772, 2010). "Nonconservative missense mutations in SUFU (orthologous to the gene mutated in the zebrafish dre mutants) have been observed in independently isolated medulloblastomas and are therefore associated with cancer." (PMID 17397257, 2007). "Looking at those patients who presented with an SHH activated medulloblastoma aged 3.5 years and younger as well as assuming SHH activation for all our Gorlin patients, approximately 17% of them would have tested positive for a pathogenic PTCH1 or SUFU mutation." (PMID 34888241, 2021). "Similarly, ATM, NBN, PALB2, PMS2, PTCH1, and SUFU are tumor suppressor and germline risk genes for medulloblastoma, but CH variants in these genes have not been found in prior studies." (PMID 32508881, 2020). "Mutations in Sonic Hedgehog (SHH) signaling pathway genes, for example, Suppressor of Fused (SUFU), drive granule neuron precursors (GNP) to form medulloblastomas (MBSHH)." (PMID 39835775, 2025). "Stabilization of GLI proteins by SUFU results in outsized SHH signaling responses, as manifested in altered limb development and medulloblastoma tumorigenesis." (PMID 38358805, 2024). "Suppressor of fused (SUFU) is widely regarded as a key negative regulator of the sonic hedgehog (SHH) morphogenic pathway and a known tumor suppressor of medulloblastoma (MB)." (PMID 38358805, 2024). "The CSGs with the most P/LP variants in cases, and significantly higher than controls, were the known medulloblastoma genes ELP1 and SUFU." (PMID 39184053, 2024).